SCN2A (sodium voltage-gated channel alpha subunit 2)
Diseases named in the same sentence as SCN2A in open-access papers (continued):
Sharing a sentence is not in itself a finding about the gene and the disease.
epilepsy (continued). "For example, SCN2A, the causative gene for epilepsy-associated Dravet syndrome, is also a primary candidate gene for familial autism, while NRXN1 has been associated with epilepsy as well as autism, schizophrenia, and developmental disability." (PMID 31653223, 2019). "The involvement of NaV1.2 in human disease has been highlighted by the identification of over 20 non-/mis-sense mutations in SCN2A in patients with seizure disorders, including BFNIS, GEFS+ 5,22,25,50,51." (PMID 29335582, 2018). "Our findings should contribute to understanding of the pathomechanisms of epilepsies in patients with SCN2A mutations and absence epilepsy itself, the mechanism of which is still not fully elucidated." (PMID 30175250, 2018). "All patients with mosaic SCN2A pathogenic variants had epilepsy and many (5/7) were also noted to have developmental delay based on limited clinical information provided." (PMID 28837158, 2018). "We identified only 6 patients with ESESS/CSWSS/epilepsy-aphasia spectrum who were reported to have SCN2A mutations." (PMID 29976148, 2018). "Mutations in the SCN2A gene encoding a voltage-gated sodium channel Nav1.2 are associated with epilepsies, intellectual disability, and autism." (PMID 30175250, 2018). "SCN2A gain-of-function mutations cause early-onset severe epilepsies, while loss-of-function mutations cause autism with milder and/or later-onset epilepsies." (PMID 30175250, 2018). "SCN2A mutations have been described in patients with a wide spectrum of epilepsies, intellectual disability and ASD." (PMID 30175250, 2018). "A SCN2A mutation has been identified to be associated with seizures, ataxia and a sensitivity to pain in epilepsy patients and patients with other neurological disorders." (PMID 24220630, 2014). "The presence of NaV1.2 in axons of inhibitory interneurons provides an explanation on why loss-of-function mutations of the Scn2a gene encoding NaV1.2 cause a genetic predisposition to epilepsy." (PMID 25203314, 2014). "For example, a combination of mutant alleles in Scn2a and Kcnq2 resulted in a much more severe epilepsy phenotype than when mutations were only present in a single gene." (PMID 19837565, 2009). "Additionally, seizures and epilepsy were prevalent, affecting 79 and 37 patients, respectively, further underscoring the neurological impact of SCN2A mutations." (PMID 40507552, 2025). "In some cases, the ASM may be targeted to the specific underlying disease mechanisms (e.g. the use of sodium channel-blocking ASMs for the treatment of seizures in individuals with SCN2A-related epilepsies due to gain-of-function variants)." (PMID 40381056, 2025). "Similarly, SCN8A-related epilepsy exhibits a range of phenotypes, with LGS associated with GOF variants, though epilepsy onset is typically later in infancy compared to SCN2A." (PMID 40310132, 2025). "Seizures and epilepsy are among the most common features of SCN2A-associated cases." (PMID 40507552, 2025). "However, patients with LOF SCN2A/NaV1.2 pathogenic variants often have more prominent autistic traits, cognitive deficits, and epilepsy." (PMID 37654020, 2024). "Our study suggests the findings of this investigation indicate that the polymorphisms SCN1A rs2298771 and SCN2A rs17183814 could potentially act as predictive biomarkers for the responsiveness to VPA among Chinese epilepsy patients." (PMID 38837984, 2024). "Although sodium channel blockers may be beneficial in the treatment of epilepsy related to GOF variants in SCN2A and SCN8A, it is also known that sodium channel blockade may induce spasms or worsen them." (PMID 38540325, 2024). "SCN2A variants could result in a wide spectrum of epilepsy, ranging from benign self-limited epilepsy to severe epileptic encephalopathy." (PMID 37152433, 2023). "In addition to epilepsy, Scn2a has also been implicated in other neurological disorders, including schizophrenia and autism spectrum disorder." (PMID 36835631, 2023).
epilepsy (continued). "Mutations in SCN2A are associated with inherited epilepsies including BFNIS." (PMID 40217485, 2023). "Despite the success of carbamazepine and high dose of phenytoin in certain cases of epilepsy resulting from SCN2A mutations, a considerable number of patients remain pharmaceutically intractable, even when treated with other traditional anti-seizure medications." (PMID 40217485, 2023). "Differences in SCN2A variant function may segregate with the age of onset of epilepsy or correlate with later onset neurodevelopmental disorders." (PMID 37578743, 2023). "Oxcarbazepine and valproate were the most effective drugs in epilepsy patients with SCN2A variants." (PMID 35431799, 2022). "In this study, we analyzed the epilepsy phenotypes of patients with SCN2A variants." (PMID 35431799, 2022). "Epilepsy caused by SCN2A variants mostly starts in early childhood and has a wide phenotypic spectrum, ranging from self-limited epilepsy with a favorable outcome to developmental and epileptic encephalopathy, and most of them respond well to sodium channel blockers (SCBs)." (PMID 35431799, 2022). "In addition, both rs4667485 and rs1469649 of SCN2A gene were significantly correlated to epilepsy risk for both allelic (4e-4 and 1e-3) and genotypic (1e-3 and 5e-3)." (PMID 35801810, 2022). "Finally, the haplotype analysis revealed that the GATGCTCGGTTTCGCTACGCA haplotype of SCN2A polymorphisms was significantly related to epilepsy increased risk, p = 6e-3, OR (CI) = 2.02 (1.23–3.31)." (PMID 35801810, 2022). "A total of 72 unrelated epilepsy patients with heterozygous SCN2A variants were collected." (PMID 35431799, 2022). "Moreover, The GATGCTCGGTTTCGCTACGCA haplotype of SCN2A gene was significantly related to epilepsy increased risk." (PMID 35801810, 2022). "Moreover, the haplotype analysis showed that the GATGCTCGGTTTCGCTACGCA haplotype of SCN2A gene was significantly related to epilepsy increased risk, p = 6e-3, OR (CI) = 2.02 (1.23–3.31)." (PMID 35801810, 2022). "We also propose that within the SCN2A gene, the C/CC of rs4667485 as well as the G/GG of rs1469649 may act as increased risk factor for epilepsy development and progression in Saudis." (PMID 35801810, 2022). "In addition, both rs4667485 and rs1469649 of SCN2A were significantly associated with epilepsy risk." (PMID 35801810, 2022). "SCN2A-related epilepsy (DEE and BFIS) is associated with different effects on channel function, and the mechanism behind this paradox is still unknown." (PMID 34093402, 2021). "In some individuals, Scn2a mutations can lead to both epilepsy and autistic features." (PMID 33484493, 2021). "At the same time, some genes such as SCN2A can be associated with a wide range of epilepsy syndromes ranging from self-limited familial neonatal epilepsy at the mild end to Ohtahara syndrome, EIFMS, West syndrome, Lennox–Gastaut syndrome, or unclassifiable DEEs at the severe end of the spectrum." (PMID 34356067, 2021). "Regions of SCN2A with functionally validated epilepsy variants with references." (PMID 33841294, 2021). "Mutations in SCN2A were related to a spectrum of epilepsies and NDDs with phenotypic heterogeneity, including developmental and epileptic encephalopathy 11 (MIM #613721); episodic ataxia type 9 (MIM #618924); and benign familial infantile seizures 3 (MIM #607745)." (PMID 34858471, 2021). "It has been proposed that within SCN2A mutations, those that cause a gain of function and increased neural excitability cause epilepsy, whereas mutations that cause loss of function, either dampening channel function or leading to haploinsufficiency, cause autism." (PMID 32264956, 2020). "Since mutations in Nav1.2 are generally believed to cause epilepsy through gains of channel function, patients whose epilepsy is reasonably attributable to a SCN2A (Nav1.2) mutation are generally expected to respond well to sodium channel blockers, such as carbamazepine, phenytoin, and lamotrigine." (PMID 32244818, 2020).
epilepsy (continued). "For example, patients with epilepsy that is driven by SCN2A mutations that enhance persistent and/or resurgent current, such as the R1882Q mutation, may benefit from this compound." (PMID 32244818, 2020). "However, the involvement of resurgent currents in the pathogenicity of epilepsy mutations of SCN2A has only recently begun to be investigated." (PMID 32244818, 2020). "To date, neuronal hyperexcitability because of GOF variants in SCN2A most likely contribute to infantile epilepsy, but how can our study explain that LOF variants (haploinsufficiency) in SCN2A diminishing or eliminating channel function also lead to DEE with relatively milder phenotype by our study?" (PMID 32400968, 2020). "Polymorphisms in the SCN2A, which may reduce this recovery action, have been associated with epilepsy and AED resistance." (PMID 32331418, 2020). "However, we did not detect a likely pathogenic sequence or copy number variant in any known epilepsy gene other than the already known SCN2A de novo variant." (PMID 30813884, 2019). "The symptoms induced by a deficiency of SCN2A are however not limited to epilepsies." (PMID 30962870, 2019). "Because disorders associated with SCN2A (epilepsy, ASD, intellectual disability, and schizophrenia) involve hyperactivity, anxiety, and seizure as important symptoms and comorbidities, we next tested locomotor behavior, anxiety-like behavior, and seizure susceptibility in Scn2a+/- mice." (PMID 31249508, 2019). "SCN2A mutations associate with two phenotypic spectrum related to epilepsy: the early onset (< 3 months) group which include benign familial neonatal or infantile seizures (BFNIS) and the late onset (> 3 months) group which include focal epilepsies with an ESESS/CSWSS-like picture." (PMID 29976148, 2018). "With the increasing numbers of drug-resistant epilepsies resulting from SCN2A and SCN8A mutations being reported, there is increasing opportunity to gather the necessary data to investigate the potential link between neurotransmitters and voltage-gated sodium channelopathies." (PMID 29184379, 2017). "Treatment of a male patient suffering from drug-resistant epilepsy, resulting from a deleterious de novo sodium voltage-gated channel alpha subunit 2 (SCN2A), gene splice-site mutation, with the 5-HT precursor 5-hydroxytryptophan, led to mild clinical improvement." (PMID 27891070, 2016). "Participants with SCN2A mutations have been identified with seizures and various forms of epilepsy." (PMID 24650168, 2014). "Interestingly, both gain- and loss-of-function mutations of the Scn2a gene encoding the NaV1.2 α subunit can be associated with some forms of epilepsy." (PMID 25203314, 2014). "This suggests that SCN2A c.R19K polymorphism may be involved in modulating the drug response in epilepsy patients." (PMID 21747585, 2011). "In our cohort, the patient carrying the SCN2A (p.I894S) missense variant presented with early-onset epileptic encephalopathy characterized by multifocal tonic and focal seizures with neonatal onset, consistent with previous reports linking Domain II S5–S6 pore-region variants to severe epilepsy." (PMID 41153369, 2025). "It’s crucial to develop pharmacotherapeutic agents for epilepsy associated with pathogenic SCN2A mutation, which function primarily by amplifying resurgent and/or persistent currents, and may get involved in selective suppression of the aberrantly enhanced resurgent and/or persistent currents." (PMID 40217485, 2023). "This could be a new mechanism causing the downregulation of SCN2A protein in epilepsy patients." (PMID 37968271, 2023). "Indeed, individuals with a LOF SNV in SCN8A/SCN2A, the genes encoding NaV1.6/NaV1.2, also exhibit epilepsy, and the concept that impaired inhibitory neuronal excitability results in epilepsy has been considered in the related disorder of FGF13, a member of the FGF homologous factor family." (PMID 37286232, 2023).
epilepsy (continued). "Like SCN1A LOF variants in Dravet syndrome, recent studies described the expression of NaV1.2 channels in inhibitory neurons, indicating the mechanism of epilepsy due to SCN2A loss-of-function variants could also be the imbalance of excitatory/inhibitory neurons." (PMID 37152433, 2023). "Similarly, sodium channel, neuronal type 2, alpha subunit (SCN2A) mutation, which is known to be associated with a broad spectrum of infant/childhood epilepsy, was detected in two patients in the current study, with mild presentation that started in the first three months of life." (PMID 37628333, 2023). "SCN2A mutations may cause neonatal-, infantile-, and childhood-onset epilepsies." (PMID 38003469, 2023). "Given the beneficial epistatic interactions between these two ion channel mutations in the context of epilepsy, in this work a battery of behavioral tests was employed to investigate whether the Scn2a and Kcna1 mutations interact to modify genotype–phenotype relationships in the context of autism." (PMID 33484493, 2021). "Resurgent currents have been shown to be enhanced by the R1882Q mutation, which is one of the most frequently reported epilepsy mutations in the SCN2A gene, and future studies may reveal the enhancement of resurgent currents to be a common effect of SCN2A epilepsy mutations." (PMID 32244818, 2020). "Thus, preferentially inhibiting resurgent and/or persistent currents in patients with SCN2A epilepsy mutations that enhance one or both of these currents may prove to be therapeutically beneficial for these patients." (PMID 32244818, 2020). "Further investigation into the differences between the two models has identified calcium/calmodulin protein kinase II (CaMKII) as a modulator of the Scn2aQ54 phenotype, suggesting the CaMKII pathway may serve as a therapeutic target for SCN2A-associated epilepsy." (PMID 32264956, 2020). "Reportedly, mutations in SCN2A could cause seizures and epilepsy." (PMID 27802793, 2017). "In SCN2A-related epilepsies, common abnormalities included atrophy (58.8%), white matter signal abnormalities (17.6%), hypoxic–ischemic encephalopathy (11.8%) and malformations of cortical development (11.8%)." (PMID 41573391, 2025). "SCN2A followed, with three confirmed cases from two families, consistent with its well-established role in epilepsy and neurodevelopmental delay." (PMID 41300846, 2025). "The neuroimaging spectrum of SCN2A-related epilepsy is notably heterogeneous and appears to correlate with clinical severity." (PMID 41573391, 2025). "KDM5C gene silencing leads to down-regulation of SCN2A, CACNA1B; CACNA1H; SCL4A3, SLC18A1, and SLC6A12, All of these KDM5C target genes have been linked to neurological disorders such as epilepsy, autism or schizophrenia." (PMID 39948613, 2025). "Animal models and clinical studies of Scn2a have been key in understanding how sodium channel dysfunctions contribute to epilepsy." (PMID 39452036, 2024). "Mutations in several NaV-α subunits were associated with epilepsy, including NaV1.1 (SCN1A), NaV1.2 (SCN2A), NaV1.3 (SCN3A), NaV1.6 (SCN8A), and NaV1.7 (SCN9A)." (PMID 39728106, 2024).
epilepsy (continued). "The role of genetic variations, specifically in sodium channels encoded by SCN1A and SCN2A genes, in influencing the effectiveness of VPA in treating epilepsy is still debated." (PMID 38837984, 2024). "Thus, WEE1 may be part of a signaling pathway, including FGF14 and Nav1.2, that, if perturbed, could contribute to endophenotypes related to neurodevelopmental disorders such as schizophrenia and SCN2A channelopathies associated with autism spectrum disorder and epilepsy." (PMID 39125637, 2024). "Five single nucleotide polymorphisms (SNPs), including SCN1A (rs10188577, rs2298771, rs3812718) and SCN2A (rs2304016, rs17183814), were genotyped in 233 epilepsy patients undergoing VPA therapy." (PMID 38837984, 2024). "In fact, pathogenic variants of SCN1A/NaV1.1, SCN2A/NaV1.1, SCN3A/NaV1.1, SCN8A/NaV1.6, and SCN1B/β1, which are expressed in the central nervous system, are important causes of different types of epilepsies, including mild and severe forms." (PMID 37654020, 2024). "Genetic variants of NaV1.1 (SCN1A), NaV1.2 (SCN2A), NaV1.3 (SCN3A), and NaV1.6 (SCN8A) sodium channels are involved in a broad spectrum of diseases, including several types of epilepsy." (PMID 37654020, 2024). "Milder forms of SCN2A related epilepsy (Benign Familial Infantile Seizures (BFISs)) are a good example of this correlation." (PMID 39513870, 2024). "The identification of multiple modifiers of Scn2a-related seizures in mice can uncover potential new targets for the treatment of SCN2A-related seizure disorders." (PMID 39606727, 2024). "Nav channel mutations are related to epilepsy, including α subunits, such as Nav1.1 (SCN1A), Nav1.2 (SCN2A), Nav1.3 (SCN3A), Nav1.6 (SCN8A), and Nav1.7 (SCN9A), and the β subunit (SCN1B)." (PMID 38174099, 2023). "For example, EA and epilepsy associations include EA1 (KCNA1), EA2 (CACNA1A), EA5 (CACNB4), EA6 (SLC1A3), SCN2A, KCNA2, ATP1A3, SLC2A1, and PRRT2." (PMID 37008993, 2023). "The meta-regression analysis showed the strongest association of SCN2A with genes in neurodevelopmental disorders, and KCNMA1 as a common gene signature with a link to epilepsy, movement disorders and wide paroxysmal neurologic presentations." (PMID 37008993, 2023). "Except for α subunit, β subunit (Scn1b), type 2 (Scn2a), and type 8 (Scn8a) have also been used as genetic models for epilepsy in mice." (PMID 36835631, 2023). "For patients suffering from early infantile epilepsies, the use of oxcarbazepine in some SCN2A-related epilepsies requires vigilance to assess the possibility of epilepsy worsening." (PMID 37152433, 2023). "In the present study, three patients with late-onset SCN2A-related epilepsy received OXC: OXC addition was ineffective in one patient, and seizures were completely controlled after OXC addition in the two others." (PMID 38174099, 2023). "The involvement of lncRNA PVT1 in epilepsy has revealed its role in promoting neuroinflammation by modulating the miR-488-3p/FOXD3/SCN2A axis." (PMID 37653173, 2023). "SCN1A, SCN2A, SCN3A, SCN8A, SCN9A, SCN11A, and SCN1B sodium channel gene mutations were intimately associated with epilepsy and displayed significant heterogeneity in pathogenesis and clinical symptoms." (PMID 38174099, 2023). "The involvement of lncRNA PVT1 in epilepsy has revealed its role in promoting apoptosis in neuronal cells by modulating the miR-488-3p/FOXD3/SCN2A axis." (PMID 37653173, 2023). "Genetic variants in SCN1A, SCN2A, and SCN1B, encoding voltage-gated sodium channels, contributed to early-onset epilepsy." (PMID 36835631, 2023). "In our study, we applied sodium channel blockers to four of six patients with early-onset SCN2A-related epilepsy, and OXC and LCS were effective in two patients each." (PMID 38174099, 2023).